LINC02470 (long independently transcribed non-coding RNA 2470)
Synonyms: AC091814.2
Gene: Long non-coding RNA gene on chromosome 12 (9,936,417 to 9,943,508, reverse strand). Ensembl gene ENSG00000225231.
Diseases named in the same sentence as LINC02470 in open-access papers:
LINC02470 is named in the same sentence as 2 diseases in open-access papers, as found by Europe PMC text mining. Sharing a sentence is not in itself a finding about the gene and the disease. The quoted sentences say what the papers report.
bladder cancer (3 papers, 2020 to 2024). "This should be clinically applicable in that higher urinary or serum exosomal LINC00960 and LINC02470 expression levels might be associated with higher pathological grade or poorer prognosis of bladder cancer patients." (PMID 32517366, 2020). "Knockdown of LINC02470 also reduced the levels of two typical mesenchymal markers, vimentin and N-cadherin, in both bladder cancer cell lines." (PMID 35205713, 2022). "The findings of the present study indicate that miR-143-3p directly targets and suppresses SMAD3 expression to inhibit the EMT process in bladder cancer cells; however, high LINC02470 expression sponges miR-143-3p to rescue SMAD3 translation and recovers the EMT process." (PMID 35205713, 2022). "First, the LINC02470–miR-143-3p–SMAD3 ceRNA axis participates in bladder cancer progression." (PMID 35205713, 2022). "Our findings indicate that exosome-derived LINC00960 and LINC02470 from high-grade bladder cancer cells promote the malignant behaviors of recipient low-grade bladder cancer cells and induce EMT by upregulating β-catenin signaling, Notch signaling, and Smad2/3 signaling." (PMID 32517366, 2020). "Moreover, higher LINC02470 expression was associated with worse overall survival of bladder cancer patients in the GSE13507 dataset; LINC02470 conferred a 2.156-fold higher risk (95% CI 1.256–3.700, p = 0.004, log-rank test) of bladder cancer-related death." (PMID 35205713, 2022). "Thus, T24-Exos or J82-Exos-derived LINC00960 and LINC02470 could be important aggressiveness-promoting factors in bladder cancer progression." (PMID 32517366, 2020). "Furthermore, we identified two novel exosomal lncRNAs, LINC00960 and LINC02470, that both play pivotal roles in the EMT process and promote the aggressiveness of bladder cancer cells." (PMID 32517366, 2020). "Knockdown of LINC00960 or LINC02470 in high-grade cells reduced these aggressive traits and signaling activations in low-grade recipient cells, thus suggesting that LINC00960 and LINC02470 could be valuable biomarkers for monitoring bladder cancer progression." (PMID 39039064, 2024).
cancer (1 paper, 2022). A tumor composed of atypical neoplastic, often pleomorphic cells that invade other tissues. "Only LINC02470 revealed a pattern similar to the screening criterion: it was expressed at lower levels in both low-grade cancer cell lines but at higher levels in both high-grade cancer cell lines." (PMID 35205713, 2022). "LINC02470 and SMAD3 were more highly expressed in high-grade cancer cells with higher mesenchymal-like traits, such as higher N-cadherin and vimentin expression but lower E-cadherin and cytokeratin 18 expression." (PMID 35205713, 2022). "Conversely, LINC02470 and SMAD3 were expressed at lower levels in low-grade cancer cells or nontumor cells with higher epithelial-like traits, such as higher E-cadherin and cytokeratin 18 expression but lower N-cadherin and vimentin expression." (PMID 35205713, 2022).